INS (insulin)
Diseases named in the same sentence as INS in open-access papers (continued):
Sharing a sentence is not in itself a finding about the gene and the disease.
breast cancer (continued). "In breast cancer, although both IGFs and insulin have been reported to regulate cell growth, most of the therapeutic agents have targeted IGF-1R function." (PMID 29152592, 2017). "We had also limited power to investigate the duration/dose of insulin exposure and the effect on breast cancer subtype." (PMID 28076434, 2017). "We subsequently established a cell model that involved breast cancer cells cultured in 50 IU/L human insulin medium for 48 hours." (PMID 28427228, 2017). "Significantly, we have previously shown that IGF-1, IGF-2 and insulin induce DDR1 upregulation in breast cancer cells by activating the AKT/miR199a-5b pathway." (PMID 28591735, 2017). "Insulin promotes breast cancer cell proliferation and migration through the extracellular-regulated kinase (ERK) pathway." (PMID 28427228, 2017). "A large number of epidemiological studies have found that the blood insulin levels or fasting C peptide levels of breast cancer patients were significantly higher than those of individuals in the normal population." (PMID 28427228, 2017). "The breast cancer cell models in high-insulin cultures were established by identifying the insulin concentration in which and time at which the maximum rate of cell proliferation occurred." (PMID 28427228, 2017). "Increasing amounts of evidence show that insulin can activate different insulin signaling pathways to promote breast cancer growth and invasion." (PMID 28427228, 2017). "For instance, experimental models show that modification of insulin levels associated with glycemic dysregulation appears early during cancer development: Pancreatic carcinogenesis and breast cancer are preceded by modifications of blood insulin levels." (PMID 28717385, 2017). "This is the first study in which a human relevant breast cancer mouse model has been used to study the tumorigenic effects of chronic insulin analogue treatment." (PMID 28173837, 2017). "For translational purposes, we ran the same classifiers on transcriptomic (micro-array) data of insulin analogue-exposed human breast cancer cell lines." (PMID 28173837, 2017). "Herein, we showed that human insulin increased miR-29a expression in ER-positive breast cancer cells and that miR-29a facilitated the ability of insulin to promote breast cancer cell proliferation and migration." (PMID 28427228, 2017). "Some studies have found that insulin plays an important role in carcinogenesis and breast cancer development by promoting mitosis or resistance to apoptosis or by affecting the sex hormone environment in vivo." (PMID 28427228, 2017). "According to these findings, DDR1 enhanced breast cancer cell proliferation, invasion and colony formation in response to insulin and IGF-2." (PMID 28591735, 2017). "The data presented here shows the relationship between pre-existing use of insulin secretagogue, the inflammatory C–C chemokine profiles at the time of breast cancer diagnosis, and subsequent cancer outcomes." (PMID 28275673, 2017). "Insulin further stimulates the production of estrogen and the expression of ER-α in breast cancer cells." (PMID 28765555, 2017). "In agreement with clinical observations, in vitro heparanase enzyme augmented INSR signaling / downstream AKT activation in breast carcinoma cell lines, and enhanced insulin-induced growth of breast tumor cells." (PMID 28038446, 2017). "Here we present the evidence that activity of heparanase enzyme (the only known mammalian endoglycosidase that cleaves HS) leads to enhanced insulin signaling and activation of downstream tumor-promoting pathways in breast carcinoma cells." (PMID 28038446, 2017).
breast cancer (continued). "We demonstrate that heparanase activity leads to enhanced insulin signaling and activation of downstream tumor-promoting pathways in breast carcinoma cells." (PMID 28038446, 2017). "In summary, our findings suggest that variation in genes in the insulin, IGF, GH, and LEP pathways contribute to the risk of breast cancer and, in particular, to ER-negative breast cancer in African-American women." (PMID 27942580, 2016). "Nonetheless, as large scaled epidemiological studies imply existing association between insulin usage and breast cancer incidence and mortality, further research to evaluate the potential effect of insulin on breast cancer is needed." (PMID 27648070, 2016). "We conducted gene-based analyses of 184 genes in the insulin/IGF, growth hormone, and leptin pathways to identify genetic variation associated with risk of breast cancer overall, and for estrogen receptor (ER) subtypes." (PMID 27942580, 2016). "Regulated by Erb-B2 receptor tyrosine kinase 2 and insulin, induce a metabolic shift in breast cancer cells." (PMID 27551267, 2016). "Now, we have shown that Sam68 plays a role in leptin and insulin signal transduction pathways in three different adenocarcinoma breast cancer cell lines." (PMID 27415018, 2016). "Leptin and insulin have previously been demonstrated to activate these pathways in cancer and, specifically, breast cancer cells." (PMID 27415018, 2016). "BYL719-resistant breast cancer cells showed a high dependency on the insulin pathway; removal of insulin from the medium was sufficient to abrogate resistance." (PMID 27048245, 2016). "Increased BMI favors the elevation of insulin and growth fator similar to insulin (IGF), and is associated significantly with an increased risk of breast cancer development and progression of disease." (PMID 27310615, 2016). "PI3K/AKT, MAPK kinase and insulin pathways are frequently described in breast cancer, which downstream targets control cell proliferation, cell survival and glucose metabolism." (PMID 27813494, 2016). "Forced expression of Klotho was previously shown to inhibit MCF7 breast cancer cell growth by inhibiting insulin/IGF-1/AKT signaling." (PMID 26556877, 2016). "We have confirmed the growth promoting effect of insulin and leptin in breast cancer cells, as well as the importance of Sam68 expression to exert this effect, since down-regulation of Sam68 impairs the proliferative action of both hormones." (PMID 27415018, 2016). "Biological effects of leptin and insulin in promoting growth and proliferation have been extensively reported in many different cell systems, including breast cancer cells." (PMID 27415018, 2016). "In the present work we have confirmed the Tyr-phosphorylation of Sam68 upon insulin and leptin stimulation in three different breast cancer cell lines." (PMID 27415018, 2016). "In fact, estrogenic stimulation promotes breast cancer pathogenesis and tumorgenesis, while insulin and leptin exhibit proliferative, mitogenic, and anti-apoptotic activities in mammary cells, thus promoting tumor growth." (PMID 27464488, 2016). "In vitro studies suggested that insulin promoted growth of the ER+ human breast cancer cell lines and the effects of insulin on ER- human breast cancer cell lines are quite complex and inconsistent with limited number of cell lines." (PMID 25679392, 2015). "The “Women’s Health Initiative Study” showed that women exhibiting insulin levels in the upper tertile were more than twice as likely to develop breast cancer compared with those presenting insulin levels in the lowest tertile." (PMID 25798130, 2015). "Both IGF-1 and insulin are mitogenic and anti-apoptotic for human breast epithelium and also human breast cancer cells; human breast cancer cells often overexpress IGF-1 receptor and insulin receptor." (PMID 26030767, 2015).
breast cancer (continued). "The hazard ratios for breast cancer mortality for insulin use for ≥3 years were consistently and significantly higher than that in the comparison groups in all analyses." (PMID 26171401, 2015). "With a collagen invasion assay it was determined in several breast cancer cell lines that AspB10 has an increased invasive capacity compared to human insulin." (PMID 26242987, 2015). "Leptin secretion from adipose tissue is believed to promote breast cancer directly and independently and also through its effects on estrogen and insulin signaling pathways." (PMID 26251693, 2015). "Some in vitro and observational studies provide evidence for a potential link between insulin and breast cancer." (PMID 26537234, 2015). "Evidence on the potential pathways involved in insulin-analogue-induced breast cancer mitogenesis is limited." (PMID 26242987, 2015). "This variation induced by our insulin treatment conditions probably provides a better representation of human breast cancer in general and EMT tumors in particular." (PMID 25848982, 2015). "Similar to breast cancer cells, in vitro studies have shown that endometrial cancer cell lines increased proliferation by activation of insulin, IGF-1, and ovarian steroid hormone signaling pathways, such as estrogen and androgen signaling pathways." (PMID 25866823, 2015). "The postmenopausal women with insulin levels in the upper tertile were more than twice as likely to develop breast cancer as those in the lowest tertile." (PMID 26516917, 2015). "The uncertainty surrounding the extent to which a registered prescription dispensed for an insulin analogue reflects real life use of insulin analogues limits the ability to detect the true effect on the occurrence of breast cancer." (PMID 26242987, 2015). "Only one study investigated the effect of cumulative dose and duration of insulin treatment on breast-cancer-specific survival, and found lower mortality from breast cancer." (PMID 26242987, 2015). "Breast cancer tissues showed increased levels of the “A” isoform of the IR (IR-A) activated by insulin and IGF." (PMID 25866823, 2015). "Overall, only IR, IGF1R, p-Erk or p-Akt levels were significantly affected in insulin analogue treatment-related mammary tumor." (PMID 25848982, 2015). "In vitro studies have shown that only insulin AspB10 and glargine have increased mitogenic potential compared to regular human insulin in breast cancer cell lines." (PMID 26242987, 2015). "Among these genes, AP3B1, ONECUT2 and IL-6 were already confirmed to be direct targets of miR-9 in breast cancer, insulin-producing cells, and cervical adenocarcinoma, respectively, which demonstrated the reliability of our screening strategy." (PMID 26547929, 2015). "The results of the current study suggest that serum insulin and tumor IR, p-Akt, and Ki-67 should be evaluated as potential biomarkers of metformin tumor sensitivity in this and other metformin trials in breast cancer." (PMID 26111812, 2015). "This is an unexpected result given that, as discussed later, insulin is a mitogen for breast cancer epithelial cells." (PMID 26516917, 2015). "Our results are consistent with an important role played by insulin-axis proteins in the pathogenesis of breast cancer." (PMID 25619494, 2015). "In breast cancer, insulin induces aromatase activity and reduces sex hormone binding globulin (SHBG), leading to increased free oestrogen levels, which in turn increases mitogenicity." (PMID 26541196, 2015). "Yet, future studies in mouse models that lead to more human relevant tumors remain important to fully exclude a role for current clinically relevant insulin analoques in the development and/or progression of human breast cancer." (PMID 25848982, 2015). "The mitogenic effect of insulin on mammary tumors was first demonstrated more than 40 years ago, when researchers found that insulin-deficiency reduced chemically induced mammary tumor growth in rats." (PMID 26029167, 2015).
breast cancer (continued). "Glargine was the only clinically available insulin analogue for which an increased proliferative potential was found in breast cancer cell lines." (PMID 26242987, 2015). "Insulin itself exerts a mitogenic effect on various tissues including breast cancer cell lines, which are usually oestrogen receptor positive." (PMID 26541196, 2015). "Previous studies have indicated that estrogens increase insulin sensitivity and stimulate glucose uptake in target tissues and breast-cancer cells." (PMID 25798130, 2015). "In this study, we demonstrate that treatment of MCF7 breast carcinoma cells with either insulin or insulin-like growth factor affects the subcellular localization of MIER1α." (PMID 26281834, 2015). "Our data demonstrate that insulin and IGF-1 can contribute to loss of nuclear MIER1α in the MCF7 breast carcinoma cell line." (PMID 26281834, 2015). "Reliability of insulin and/or C-peptide levels as biomarkers of breast cancer has been a subject of controversy." (PMID 24911052, 2014). "In the same line of evidence a kinome-wide screen in breast cancer identified the insulin and IGF pathway as an escape mechanism from hormone dependence in estrogen receptor positive breast cancers." (PMID 24809298, 2014). "Because XMetS enhanced the binding affinity of the INSR for insulin, we studied the effect of XMetS on insulin-stimulated proliferation of MCF-7 human breast cancer cells." (PMID 24533136, 2014). "In MCF-7 human breast cancer cell line, methotrexate-induced cytotoxicity increased as much as 10,000-fold when combined with insulin." (PMID 24885964, 2014). "To test the impact of Wnt on miR-29 in breast cancer cells, we treated T47D cells independently with Wnt3a or insulin and found a noticeable increase in levels of miR-29 a and b." (PMID 25174825, 2014). "Addition of insulin to an asynchronous population of breast cancer cells increased the S-phase fraction to 66% compared to 37% in the controls." (PMID 24885964, 2014). "While this effect is clearly multifactorial and may be linked to changes in sex hormone levels, insulin, adipokines and inflammatory response, leptin reduction may play a role in the achieved outcome and our data show a new mechanism of leptin-mediated effect on breast cancer signalling." (PMID 25482303, 2014). "Third, insulin has been shown to have a mitogenic effect upon breast cancer cells in vitro through several mechanisms." (PMID 25653879, 2014). "This study highlights the p85αPI3KS83 role as a key regulator of cell proliferation and motility induced by insulin in MCF-7 cells breast cancer model." (PMID 25114970, 2014). "The aim of this work was to analyze the role of the SH3 domain of p85αPI3K in insulin signalling, used as model the breast cancer cell line MCF-7." (PMID 25114970, 2014). "In addition, factors regulating the ossification process, such as insulin, insulin-like growth factor type 1, insulin-like growth factor type 2, and insulin-like growth factor binding protein 3, may also have association with the breast cancer risk." (PMID 24069386, 2013). "Estrogen and progesterone unresponsive breast cancers are mostly dependent on growth factors (i.e., insulin, insulin-like growth factor-I) and adipokines (i.e., leptin)." (PMID 24202338, 2013). "Insulin also induces leptin expression in breast cancer cells by increasing HIF-1α and SP1 binding to the leptin promoter." (PMID 24202338, 2013). "Initial experiments demonstrated that in human breast cancer cell lines insulin has been shown to promote DNA synthesis, suggesting a mitogenic effect." (PMID 23497533, 2013). "Transferase activity has been shown to be related to breast cancer as well as the level of insulin secretion." (PMID 23627667, 2013). "This is in contrast other studies in breast cancer survivors who reported correlations between physical activity and several metabolic variables including fasting insulin, HOMA-IR, CRP, leptin, IGF-I and IGFBP-3." (PMID 23855321, 2013).
breast cancer (continued). "These conditions lead to elevated glucose blood concentration, increased secretion of insulin and induction of ER+ breast cancer cell lines." (PMID 23750285, 2013). "Nevertheless, further studies with larger sample size are needed to assess the validity of novel strategies both for breast cancer chemoprevention and therapy based on targeting insulin signaling pathways." (PMID 23981814, 2013). "In rat models with chemical induction of cancer, treatment with insulin enhanced growth of azyoxymethane-induced colon tumors and 7,12-dimethylbenz(a)anthracene-induced mammary tumors." (PMID 24260289, 2013). "A recent patent reports on the invention of a pharmaceutical combination of an insulin sensitivity enhancer and a phosphoinositide 3-kinase inhibitor for the treatment of solid tumors, including breast cancer." (PMID 23061769, 2013). "Based on studies of endometrial and breast cancer tissue, we can observe a profound and complex crosslink between estrogen, progesterone, insulin or IGF-1 and its receptors." (PMID 24308813, 2013). "We performed a chart review of 79 surgically treated breast carcinoma patients (mean age of 66.5 years; range 38-86 years) who were on insulin." (PMID 24131755, 2013). "Elevated insulin can directly promote breast cancer cell growth and proliferation, and it can indirectly regulate a variety of factors, including insulin-like growth factors, sex hormones, and adipokines." (PMID 22919369, 2012). "In summary, we have used a hyperinsulinemic mouse model to study the effect of elevated systemic insulin levels on mammary tumor metastasis to lung." (PMID 22226054, 2012). "Using this assay, we performed a detailed pharmacological analysis of PIP3 production induced by IGF1, insulin and insulin analogues in living breast cancer-derived MCF-7 and MDA-MB231 cells." (PMID 22848683, 2012). "Insulin can up-regulate c-Myc in the estrogen-driven human breast cancer cell line MCF-7, which is augmented by the addition of estradiol." (PMID 22226054, 2012). "As well as confirming previously published data whereby insulin accelerates primary tumor growth, we also provide important new findings which suggest that insulin also affects breast cancer progression to the metastatic stage." (PMID 22226054, 2012). "We previously demonstrated that over expression of breast cancer oncogenes transforms MCF10A cells to an insulin-independent phenotype." (PMID 21437235, 2011). "Of significance, we have observed the insulin-independence phenotype in most of the human breast cancer cell lines developed in our laboratory." (PMID 21437235, 2011). "This indicates that insulin-independence is a common in vitro phenotype of oncogene-transformed human breast cancer cells." (PMID 21437235, 2011). "It was previously shown that cath-D expression was stimulated by insulin in epithelial breast cancer cells." (PMID 21311773, 2011). "Work conducted primarily over the past 3 decades has unravelled the presence of insulin in human breast cancer tissues and, more recently, in human non-small cell lung carcinomas (NSCLC)." (PMID 21457557, 2011). "Fourth, firm conclusions on the associations of insulin and HOMA-IR with breast cancer recurrences cannot be drawn in the presence of decreased power due to separate analyses by hormonal receptor status." (PMID 21450081, 2011). "Most of the breast cancer cell lines we examined were insulin-independent for proliferation; the one exception being the SUM44 cell line, which expressed high VAMP8 levels and also required insulin." (PMID 21437235, 2011). "Insulin has been demonstrated to have mitogenic effects on breast tissue, and insulin receptors are frequently over-expressed in breast cancer cells." (PMID 20184722, 2010). "It was suggested that this dual action of metformin (insulin reduction and mTOR inhibition) makes it a particularly attractive target for evaluation in breast cancer as well as some other, e.g. colon cancer." (PMID 21084729, 2010).